TNFSF4 (TNF superfamily member 4)
Description:
Cytokine that binds to TNFRSF4. Co-stimulates T-cell proliferation and cytokine production.
Synonyms: CD252; TXGP1; OX-40L; gp34; CD134L; OX4OL; TNLG2B
Tractability: Antibody: a drug acting on it is in phase 2 or 3 trials; its Gene Ontology location is reachable by antibodies, with high confidence; UniProt predicts a signal peptide or a membrane-spanning region.
Target class: Secreted protein
Gene: Protein-coding gene on chromosome 1 (173,162,645 to 173,477,583, reverse strand). Ensembl gene ENSG00000117586.
Subcellular location: Membrane
Subcellular location (Human Protein Atlas): Nucleoplasm; Vesicles
Pathways (Reactome):
Immune System: TNFs bind their physiological receptors
Gene Ontology:
Molecular function: protein binding; signaling receptor binding; tumor necrosis factor receptor superfamily binding; cytokine activity; tumor necrosis factor receptor binding
Biological process: cellular response to lipopolysaccharide; cellular response to prostaglandin E stimulus; negative regulation of interleukin-17 production; positive regulation of inflammatory response; positive regulation of interleukin-4 production; positive regulation of interleukin-6 production; positive regulation of type II interferon production; acute inflammatory response; defense response to nematode; inflammatory response; memory T cell activation; negative regulation of regulatory T cell differentiation; negative regulation of T-helper 1 cell differentiation; negative regulation of transcription by RNA polymerase II; negative regulation of type II interferon production; positive regulation of alpha-beta T cell proliferation; positive regulation of B cell activation; positive regulation of CD4-positive, alpha-beta T cell costimulation; positive regulation of CD4-positive, alpha-beta T cell differentiation; positive regulation of cell population proliferation; positive regulation of chemokine production; positive regulation of cytokine production; positive regulation of immunoglobulin mediated immune response; positive regulation of immunoglobulin production; positive regulation of interleukin-10 production; and 17 more
Cellular component: cell surface; extracellular region; plasma membrane; membrane
Genetic constraint (gnomAD): Loss-of-function variants: 1 observed, 4.78 expected, observed/expected ratio (o/e) 0.21, 90% interval 0.073 to 0.99. That is too few expected variants to judge how well the gene tolerates losing a copy. Missense variants: 152 observed, 195.92 expected, observed/expected ratio (o/e) 0.78, 90% interval 0.68 to 0.89. Synonymous variants: 68 observed, 83.51 expected, observed/expected ratio (o/e) 0.81, 90% interval 0.67 to 1.
Homologues: Orthologues: chimpanzee TNFSF4 (99% identical), macaque TNFSF4 (99% identical), pig TNFSF4 (69% identical), dog TNFSF4 (68% identical), rabbit TNFSF4 (64% identical), guinea pig TNFSF4 (60% identical), rat Tnfsf4 (46% identical), mouse Tnfsf4 (44% identical).
Diseases named in the same sentence as TNFSF4 in open-access papers:
TNFSF4 is named in the same sentence as 203 diseases in open-access papers, as found by Europe PMC text mining. Sharing a sentence is not in itself a finding about the gene and the disease. The quoted sentences say what the papers report.
asthma (37 papers, 2011 to 2025). "TNFSF4 is also found as a risk allele in GWAS on allergies, such as asthma, hay fever, and eczema; an observation consistent with the importance of Ox40–Ox40L pathway for Th2 response." (PMID 30061896, 2018). "GWAS studies have shown that TNFSF4 is associated with AD, asthma, SLE, and RA." (PMID 39297883, 2024). "One of the interesting genes is TNFSF4 (OX40L) which plays a role in modulating airway inflammation in asthma." (PMID 37186423, 2023). "TNFSF8/TNFSF15 and TNFSF13 loci are also associated with the risk of IgA nephropathy, while TNFSF4/TNFSF18 locus has previously been associated with the risk of eczema, asthma and narcolepsy, all with concordant effects to IgA levels." (PMID 36369178, 2022). "Prioritization of druggable genes reveals known (IL4R, TSLP, IL6, TNFSF4) and potentially new therapeutic targets for asthma." (PMID 34103634, 2021). "In contrast to our expectation, 6 asthma SNPs showed nominal association with lower eosinophil counts in the general population (rs1233578 [ZBED9], rs519973 [BCL6], rs7686660 [USP38], rs6691738 [TNFSF4], rs2507978 [HLA‐B], rs3117098 [HCG23]), and 1 SNP in the asthma population (rs2786098 [CRB1])." (PMID 37186423, 2023).
autoimmune disease (37 papers, 2011 to 2025). A disorder resulting from loss of function or tissue destruction of an organ or multiple organs, arising from humoral or cellular immune responses of the individual to their own tissue constituents. "OX40L is encoded by the TNF superfamily member 4 (TNFSF4) gene, and polymorphisms within this gene have been linked to various autoimmune diseases, including Sjögren’s syndrome, systemic lupus erythematosus, and systemic sclerosis (SSc)." (PMID 38790215, 2024). "Previous research has demonstrated that polymorphisms in the TNFSF4 gene can increase susceptibility to various autoimmune diseases." (PMID 38724875, 2024). "Here we focus on three genes, STAT4, IRF5, and TNFSF4, which are identified and validated as risk loci in GWAS in multiple autoantibody mediated autoimmune diseases with a strong disease association at the genome-wide p value of at least 5 × 10−8." (PMID 30061896, 2018). "The TNFSF4 locus (that encodes OX40L) shows association with several autoimmune diseases; it has one of the most consistent and strongest genetic risk factors in SLE." (PMID 28818832, 2017). "Genetic variations at TNFSF4 have been reported to be associated with autoimmune disorders, such as SLE and certain inflammatory conditions, including atherosclerosis and RA." (PMID 29285231, 2017). "Genetic variation at TNFSF4 has been associated with the autoimmune disease systemic lupus erythematosus (SLE), and other inflammatory conditions including atherosclerosis and ischaemic stroke." (PMID 23874208, 2013). "We previously established an 80 kb haplotype upstream of TNFSF4 as a susceptibility locus in the autoimmune disease SLE." (PMID 23874208, 2013). "Abnormal expression of OX40 and its cognate ligand OX40L (TNFSF4) have been associated with various autoimmune diseases, indicating that blocking the OX40/OX40L pathway could be a promising strategy for the treatment of a broad range of T cell-mediated autoimmune diseases." (PMID 40417257, 2025). "Previous studies have shown that polymorphisms of TNFSF4 can confer risk to diverse autoimmune diseases, such as SLE, RA, SSc and pSS, but it remains unknown whether genetic mutations of TNFSF4 region may induce occurrence of AITDs, which attracts our interest." (PMID 27556446, 2016). "Almost all variants identified (ZNF365, TNFSF4, NAB1, IKZF4-ERBB3, CTSC, DENND1B, SIRPG, and PRF1) are the same or strongly linked with markers associated with other autoimmune diseases." (PMID 37188663, 2023). "Thus, the TNFSF4/OX40L axis has emerged as a pivotal and tunable therapeutic target spanning a broad spectrum of human diseases, including autoimmune disorders, chronic inflammation, and malignancies." (PMID 41471849, 2025). "Previous studies have shown the important role of TNFSF4 in the development of autoimmune diseases." (PMID 27872495, 2016). "Single nucleotide polymorphisms (SNPs) in TNFSF4 and ANKRD55 genes have been shown to be associated with several autoimmune diseases, although whether these genes are susceptibility genes for dermatomyositis/polymyositis (DM/PM) has, to date, not been reported." (PMID 28470010, 2017). "The interaction between TNFSF4 and its ligand, OX40, plays an important role in the pathogenesis of autoimmune diseases and cancers." (PMID 35769457, 2022).
melanoma (30 papers, 2013 to 2026). A malignant, usually aggressive tumor composed of atypical, neoplastic melanocytes. "More specifically, low expression of TNFSF4 mRNA was associated with worse prognosis in melanoma patients." (PMID 35780190, 2022). "The previous study using The Cancer Genome Atlas and the Cancer Cell Line Encyclopedia RNA sequencing data from anti-PD1-treated patients with melanoma demonstrated that the low TNFSF4 mRNA expression group was associated with worse prognosis and showed a worse outcome after anti-PD1 treatment." (PMID 36694264, 2023). "In all melanoma patients and in the stage III and IIIc-IV patient cohorts, low expression of TNFSF4 was associated with a poorer prognosis." (PMID 37858131, 2023). "It was shown in both ex vivo patient samples and in that a humanized melanoma mouse model that pDC in melanoma are directed toward a TH2 promoting phenotype by induction of the molecules OX-40L (TNFSF4) and ICOSL (inducible T cell costimulator ligand), which then drive tumor progression." (PMID 29276510, 2017). "Consistently, the low expression of TNFSF4 correlated with a worse prognosis and outcome of anti-PD1 therapy in patients with melanoma." (PMID 39201666, 2024). "Indeed, we found that the gene TNFSF4, coding for the immunoregulatory protein OX40L, was a putative target of 3 of the pEV-microRNA melanoma signature, namely miR-412-3p, miR-507 and miR-1203." (PMID 36243798, 2022).
systemic lupus erythematosus (30 papers, 2011 to 2026). An autoimmune multi-organ disease typically associated with vasculopathy and autoantibody production. "An example of heterogeneity is the relationship between genetic variants from the BLK and TNFSF4 genes in systemic lupus erythematosus." (PMID 33901204, 2021). "We have established one of these, the tumour-necrosis family superfamily member 4 (TNFSF4) gene, as a lupus susceptibility gene in Northern Europeans." (PMID 23874208, 2013). "We have previously shown single nucleotide polymorphisms (SNPs) in the 5′ TNFSF4 region to be associated with lupus in European families and a case-control cohort." (PMID 23874208, 2013). "In a complementary strategy we perform association analysis using TNFSF4 alleles and lupus phenotypes." (PMID 23874208, 2013). "Association of rs2205950-T with African-American lupus concurs with data published previously by our group establishing a 5′ TNFSF4 association with SLE in Northern Europeans." (PMID 23874208, 2013). "Association testing of TNFSF4 variants revealed strong association of 5′ variants with disease in all cohorts establishing it as a global lupus susceptibility gene." (PMID 23874208, 2013). "Sanchez and colleagues use TNFSF4 rs2205960 and single markers at 15 other lupus susceptibility loci to illustrate correlation of Amerindian ancestry with increased frequency of lupus risk alleles." (PMID 23874208, 2013). "The SNPs of TNFSF4 were associated with renal involvement in lupus patients from the Chinese population (P values for rs2205960 and rs10489265 were 0.014 and 0.005 in additive model, resp)." (PMID 23936824, 2013). "In humans, the TNFSF4 has been linked to systemic lupus erythematosus." (PMID 39943110, 2025). "TNFSF4 increases the risk of myocardial infarction and systemic lupus erythematosus in humans." (PMID 36699607, 2022). "Moreover, reports have shown that TNFSF4 polymorphisms are associated with multiple autoimmune diseases, such as Sjogren’s syndrome and systemic lupus erythematosus." (PMID 30797237, 2019). "Underrepresentation of distal 5′ TNFSF4 alleles in lupus individuals with early age of onset is found in AA (P = 9×10−4, OR = 0.69 (95% CI 0.56–0.86)), European (P = 1.43×10−3, OR = 0.78(0.68–0.91)) and Hispanic (P = 1.43×10−3, OR = 0.57(95% CI 0.41–0.81)) populations." (PMID 23874208, 2013). "A recent phenotypic association study of genetic susceptibility loci in SLE suggested that TNFSF4 gene might predict renal disorder in lupus patients." (PMID 23936824, 2013). "Meanwhile, a meta-analysis study demonstrates that TNFSF4 rs2205960 SNP may confer susceptibility to SLE (systemic lupus erythematosus) in different populations and that the TNFSF4 rs1234315 SNP is associated with the susceptibility to SLE in Asian and Malaysian populations." (PMID 30797237, 2019). "In systemic lupus erythematosus (SLE), the frequency of minor T alleles of TNFSF4 rs2205960 is associated with autoantibody production and is important in Chinese and Indian patients." (PMID 33584705, 2020). "TNFSF4 (encodes OX40L) is a susceptibility locus for systemic lupus erythematosus (SLE)." (PMID 28818832, 2017). "Our data suggest a putative role for TNFSF4 in autoantibody generation, further clarifying the role of this gene in lupus pathogenesis." (PMID 23874208, 2013). "In the current study, we replicated for the first time the association between TNFSF4 and the risk of renal disorder in lupus patients from non-European populations." (PMID 23936824, 2013).
atherosclerosis (26 papers, 2011 to 2025). A disease characterized by the build-up of fatty material and calcium deposition in the arterial wall resulting in partial or complete occlusion of the arterial lumen. "In this study we investigated the association of two TNFSF4 SNPs, rs1234313 and rs45454293, with the occurrence of atherosclerosis." (PMID 30797237, 2019). "Of note, the gender-specific effect of TNFSF4 is also present in mice, female mice being more susceptible to atherosclerosis than male mice." (PMID 21445270, 2011). "Based on a mouse atherosclerosis model to positionally identify potential human candidate genes, we have provided evidence that genetic variation in the TNFSF4 gene contributes to the risk of developing myocardial infarction (MI)." (PMID 21445270, 2011). "Notably, Tumor necrosis factor superfamily member 4 (TNFSF4) is a gene affecting atherosclerosis susceptibility and encodes OX40 ligand." (PMID 33855020, 2021). "Additionally, for TNFSF4, which encode OX40L, its mutation downregulated the risk of atherosclerosis and myocardial infarction." (PMID 34900670, 2021). "However, only Metf and A-76 group identified DEGs directly associated with atherosclerosis (only two gene were involved, including Tnfsf4 and Olr1)." (PMID 28178661, 2017). "Moreover, TNFSF4 has been implicated in the development of atherosclerosis." (PMID 38724875, 2024). "However, few studies have investigated the association of TNFSF4 SNPs and atherosclerosis." (PMID 30797237, 2019). "In addition, TNFSF4 expression is associated with an increased risk of atherosclerosis." (PMID 30797237, 2019). "However, it is still unclear whether TNFSF4 gene polymorphisms are associated with the risk of atherosclerosis in the Han Chinese population." (PMID 30797237, 2019). "In line with this, SIRT6 was shown to decrease the expression of atherosclerosis‐inducing factors such as TNFSF4 (tumor necrosis factor superfamily member 4), by deacetylating H3K9 at their promoter." (PMID 39215785, 2025). "Genetic evidence reveals that the Tnfsf4 gene (encoding OX40L), located within the murine atherosclerosis susceptibility locus Ath1, is critically linked to plaque progression." (PMID 41268556, 2025). "TNFSF4 functions as a T cell co-stimulatory molecule, and is involved in the formation of atherosclerosis." (PMID 30797237, 2019). "The receptor/ligand interactions play a central role in atherosclerosis, hence TNFSF4 / TNFRSF4 interaction/interrupt can be used as a new treatment method for atherosclerosis." (PMID 30797237, 2019). "Tumor necrosis factor superfamily member 4 (TNFSF4), also known as Ox40 ligand (Ox40l), plays an important role in atherosclerosis development." (PMID 29921578, 2018). "RNA-sequencing profiling revealed that SIRT6 overexpression decreased the expression of multiple atherosclerosis-related genes, including proatherogenic gene TNFSF4 (tumor necrosis factor superfamily member 4)." (PMID 27249230, 2016). "Further support for a role of TNFSF4 in atherosclerosis was obtained in a study where blockage of the TNFSF4/TNFRSF4 interaction reduced lesion formation in low-density lipoprotein (LDL) receptor-deficient mice." (PMID 21445270, 2011). "Additionally, the expression of tumor necrosis factor superfamily member 4 (TNFSF4, also known as OX40 L), a risk factor for atherosclerosis, was reduced by SIRT6 under normal conditions or after TNF-α stimulation." (PMID 36465178, 2022). "SIRT6 inhibits atherosclerosis by deacetylating H3K9 on the promoter of the TNFSF4 gene." (PMID 33855020, 2021). "The expression of TNFSF4 has been observed in T cells, B lymphocytes, vascular endothelial cells, macrophages, mast cells, and smooth muscle cells, all of which are involved in the development of atherosclerosis." (PMID 29921578, 2018).
atherosclerosis (continued). "The TNFSF4/TNFRSF4 system, along with several other receptor-ligand pairs, is involved in the recruitment and activation of T-cells and is therefore tentatively implicated in atherosclerosis and acute coronary syndromes." (PMID 21445270, 2011). "The TNFSF4/TNFRSF4 system, along with several other receptor-ligand pairs, has been suggested to be involved in the recruitment and activation of T-cells and is therefore tentatively implicated in atherosclerosis and acute coronary syndromes such as MI." (PMID 21445270, 2011). "SIRT6 deacetylates and reduces the expression of tumor necrosis factor ligand superfamily member 4 (TNFSF4) to maintain endothelial cell function and mitigate atherosclerosis." (PMID 37876546, 2023).